WT1 (WT1 transcription factor)
Diseases named in the same sentence as WT1 in open-access papers (continued):
Sharing a sentence is not in itself a finding about the gene and the disease.
leukemia (continued). "Further strategies, including the transfer of WT1-specific T-cells or autologous vaccination of AML patients with the WT1 peptide, did increase anti-leukemia immune responses in relapsed or high-risk leukemia patients." (PMID 32604862, 2020). "Immunoblotting was used to test if HDACi modulate the leukemia-associated transcription factors β-catenin, Wilms tumor (WT1), and myelocytomatosis oncogene (MYC)." (PMID 31561534, 2019). "iDC-expressing tWT1 (iDCtWT1) stimulated T cells in vitro to cause WT1-dependent cytotoxicity against both autologous and HLA-matched leukemia cells, and promoted large expansion of human T cells in vivo, in immune-deficient mice." (PMID 31628525, 2019). "One of the first targets pursued clinically is Wilms tumor protein-1 (WT-1), which is overexpressed in a number of leukemias and solid tumors and encode a range of immunogenic peptide epitopes that can be used to successfully expand WT-1 specific T cells." (PMID 31447852, 2019). "Unlike other antigens commonly expressed in normal cells (such as CD33 and fms like tyrosine kinase 3 (FLT3)), WT1 is considered to be a leukemia-associated antigen." (PMID 31628525, 2019). "This technique has been used to load moDCs with one of the following leukemia-associated antigens: WT1, human telomerase reverse transcriptase (hTERT) and preferentially expressed antigen in melanoma (PRAME)." (PMID 31035598, 2019). "We chose HLA-A*02:01/VLDFAPPGA (pWT137–45) and HLA-A*02:01/RMFPNAPYL (pWT1126–134, data not shown) peptides, as they are from two of the HLA-A*02:01-restricted WT1 epitopes implicated in leukemia." (PMID 30678050, 2019). "Our AML cohort was characterized by mutations in genes with a known pathogenic role in leukemia and the identified chimeras contributed to the disease complexity, as demonstrated by the involvement of genes such as WT1 or copy-number loss of NF1." (PMID 31817495, 2019). "The aim of this study was to use a meta-analysis to determine any association between WT1 expression status and overall survival (OS), leukemia-free survival (LFS), and cumulative incidence of relapse (CIR) for patients with MDS." (PMID 29662637, 2018). "Here, we describe the hematologic phenotype of a knock-in mouse model of a Wt1 mutation (R394W), described in cases of human leukemia." (PMID 30450160, 2018). "The inhibition of WT1 gene expression causes leukemia suppression in vitro while forced expression of WT1 in mice results in leukemia induction." (PMID 29344432, 2018). "Excuding BCR-ABL CTLs, the anti-leukemia effects of WT1 specific CTL were also observed in 11 relapsed or high-risk leukemia patients who underwent allo-HSCT." (PMID 30619371, 2018). "Currently, we are conducting a phase I/II study on vaccination with DCs loaded with Wilms Tumor 1 (WT1) and preferentially expressed antigen in melanoma as leukemia-associated antigens for postremission therapy of acute myeloid leukemia (AML) patients." (PMID 29535740, 2018). "WT1 overexpresses in leukemia and a variety of solid tumors and performs an oncogenic function, and WT1 protein is one of the most superior pan-tumor-associated antigens." (PMID 28116121, 2016). "Several leukemia-associated antigens (LAAs) have been reported, which include Wilms’ tumor 1 (WT1), proteinase-3, bcr-abl or PML-RARα." (PMID 26784514, 2016). "In one patient, down-regulation of WT1 mRNA and loss of WT1 expression was observed at the moment of leukemia progression." (PMID 25699052, 2015). "The BCR-ABL fusion peptide is the predominant antigen in CML, and WT1 is also thought to be important for the identification of leukemia-associated antigens (LAAs) in CML to elicit a specific immune response in patients." (PMID 23241263, 2012). "In addition to DC vaccines, peptide vaccines targeting leukemia-associated antigens, such as WT1, are also under investigation." (PMID 40382583, 2025). "WT1, a protein involved in cell growth regulation, has been linked to leukemia development." (PMID 40382583, 2025).
leukemia (continued). "The WT1 mutations may disrupt normal hematopoietic differentiation, conferring leukemia cells enhanced self-renewal capacity and survival advantages." (PMID 41294667, 2025). "The WT1 protein is a hallmark in leukemia and plays an integral role in leukemogenesis." (PMID 40022126, 2025). "Mutations in the WT1 gene may cause abnormalities in cell growth and differentiation, which play an important role in the occurrence of leukemia." (PMID 40129984, 2025). "In addition, MSCs interfered with the secretory potential of leukemia-associated WT1- and ROR1-targeting CTL clones, inhibiting the release of IFNγ, tumor necrosis factor alpha, and IL-2." (PMID 38231344, 2024). "Co-cultures of leukemia-associated Wilm’s tumor protein 1 (WT1) and tyrosine-protein kinase transmembrane receptor 1 (ROR1)-reactive CTLs and of CD123-redirected switchable CAR T cells were prepared in the presence of MSCs and assessed for cytotoxic potential, cytokine secretion, and expansion." (PMID 38231344, 2024). "The lower specificity of post-SCT MRD by FCM compared to WT1 may be attributed to the presence of leukemia-associated immunophenotypes in regenerating bone marrow cells, reducing the sensitivity of aberrant phenotypes in identifying leukemic cells." (PMID 39274359, 2024). "In leukemia, the overexpression of the WT1 gene has been reported to cause resistance of leukemic cells to chemotherapy, which can clarify the poor prognostic significance of WT1 overexpression in pediatric BCP-ALL in this survey." (PMID 38293695, 2023). "Future studies with TCRGP armed with training data of TCRs against leukemia-associated antigens, such as WT1 and PR1, could provide crucial information on the antitumor immunity in patients with CML treated with different therapies." (PMID 36047494, 2022). "In case UPN8, the presentation and relapse leukemia shared a somatically acquired WT1 mutation." (PMID 34080325, 2021). "The problem is that CTAs are often expressed in less patients (23% for HAGE and 33% for PASD1) at AML presentation as compared with leukaemia associated antigens (LAAs), such as Survivin and WT1, which are found in most patients and can act as MRD markers in their own right." (PMID 30678059, 2019). "The administration of WT1-specific CD8+ cytotoxic T-cell (CTL) clones after Hematopoietic stem cell transplantation to relapsed or high-risk leukemia patients led to detectable long term maintenance and clinical responses without evidence of on-target toxicity." (PMID 28477011, 2017). "Moreover, these DC-induced Tregs also reduced T cell-mediated IFN-γ-production in response to the leukemia-associated antigen, WT1." (PMID 29312358, 2017). "This study provides new clues to the molecular pathways underlying high WT1 states in leukaemia." (PMID 26597595, 2016). "However, accumulating evidence has shown that overexpression of WT1 exerts an oncogenic effect in other tumors and is linked to poor prognoses in leukemia and breast cancer." (PMID 26573232, 2016). "Given Wt1 expressionin adult bone marrow and association with leukaemia, we surmised that Wt1 might play a role in adult haematopoiesis." (PMID 22216009, 2011). "The activation of the PI3K-AKT pathway has been demonstrated to upregulate WT1 mRNA levels in leukemia cells." (PMID 38944027, 2025). "Numerous studies have highlighted the potential oncogenic role of WT1 in leukemia progression, with its expression serving as a marker for leukemic cell proliferation." (PMID 40361130, 2025). "WT1 peptide is a product derived from the WT1 (Wilms’ tumor gene 1) gene, which is expressed in various malignancies, including leukemia and solid tumors." (PMID 39861694, 2025). "This immunotherapeutic intervention decreased WT1 transcripts, an indicator of leukemia cells, in 69% of participants after initial dosing and boosted immune cell functionality." (PMID 40382583, 2025).
leukemia (continued). "Initially identified in Wilms’ tumor, the WT1 gene shows elevated expression in multiple cancer types, including both leukemia and MDS." (PMID 40382583, 2025). "In this study, FLT3 and WT1 protein expression was used as markers of leukemia cell proliferation and was determined using Western blotting." (PMID 40361130, 2025). "The increased transcriptional activity of WT1 facilitated leukemia blasts’ progression into the cell cycle, promoting the transition from G1 to S phase, and ultimately resulting in increased cell proliferation." (PMID 40707954, 2025). "Recently, WT1 with increased expression in cancer cells in general and particularly in leukemia, has been considered as an antigen to apply immunotherapy." (PMID 38944027, 2025). "Koichi Kitagawa and associates revealed that Bifidobacterium longum, modified to express Wilms’ tumor 1 (WT1) protein, can elicit tumor-specific immune responses and inhibit tumor proliferation in mouse models of leukemia, prostate, and bladder cancer." (PMID 40282924, 2025). "Despite extensive research on WT1, few studies have explored the Hippo signaling pathway in leukemia." (PMID 40022126, 2025). "Taken together, the present study has provided evidence, to the best of the authors' knowledge for the first time, that the miRNA-132-3p/WT1/TGF-β1 axis is able to regulate the committed differentiation of leukemia cells into macrophages." (PMID 40327646, 2025). "Another trial with leukemia patients in remission showed improved outcomes following vaccination with DCs loaded with WT-1 mRNA." (PMID 40382583, 2025). "Given the significant roles of FLT3 and WT1 in leukemia pathogenesis, ongoing research to identify natural bioactive compounds targeting these pathways is essential, as it offers the potential for effective therapies with minimal side effects." (PMID 40361130, 2025). "The focus of the present study was therefore to investigate the role of the miRNA-132-3p/WT1 signaling axis in the differentiation of THP-1 leukemia cells into macrophages induced by PMA." (PMID 40327646, 2025). "So, the repressive effect of WT1 on SGK1 expression was specific for WT1 isoforms, at least in these non-leukemia cell lines." (PMID 40613901, 2025). "The Wilms’ tumor 1 gene (WT1) is an oncogene in various cancers including leukemia, breast cancer, glioblastoma, and DIPG." (PMID 38774284, 2024). "Phase I/II clinical trials of WT1 peptide-based immunotherapy have reported frequent clinical responses and significant tumor regression in leukemia, myelodysplastic syndrome, lung, and breast cancers." (PMID 38929778, 2024). "Wilms’ tumor protein 1 (WT1)-targeted immunotherapy has been used in patients with leukemia and solid tumors." (PMID 39509060, 2024). "Wild type WT1 is expressed sparsely in isolated sites in adult tissues, but is frequently aberrantly overexpressed in human leukemias and solid tumors." (PMID 38190392, 2024). "C1498-murine WT1—a genetically-engineered, murine leukemia cell line to express murine WT1—was used as tumor cell." (PMID 36803483, 2023). "WT1 is crucial to oncogenic survival signaling downstream of Bcr-Abl in leukemia and counteracts the cytotoxic effects of TKIs like imatinib." (PMID 37765274, 2023). "Emerging evidence characterizes WT1 as a tumour promoting factor in numerous human malignancies, including in leukaemia, breast cancer and lung cancer." (PMID 37667197, 2023). "In this manuscript, we have generated a comprehensive directory of leukemia and lymphoma cell lines well defined for characteristics of WT1 genomic alterations as well as mRNA and protein expression." (PMID 37444601, 2023). "It was previously shown that WT1-specific T cells can be generated to target leukemia cells with limited effect on normal progenitor cells." (PMID 37928542, 2023).
leukemia (continued). "In the present study, we describe a set of leukemia and lymphoma cell lines, which are carefully characterized for WT1’s unique properties and thoroughly screened for sequence alterations in WT1 and other genes important for leukemogenesis." (PMID 37444601, 2023). "Patients with leukemia and mesothelioma who received WT1 vaccination in clinical trials experienced a significant increase in immune responses and survival rates." (PMID 37345057, 2023). "STAT1 binds to the IRF promoter region in colon cancer cells, while MBD1 inhibits IRF8 expression, which is another indication evidence that WT1 in leukemia and IRF8 are anticorrelated." (PMID 37250717, 2023). "WT1 antagonistic peptides offer a promising avenue for developing WT1-targeting therapeutics in leukemia." (PMID 37765274, 2023). "Together with the information provided in this manuscript, this novel tool will support future research closer to the reality of WT1 in leukemia." (PMID 37444601, 2023). "In previous our study, wt-TCR-transduced CD4+ T cells showed cytotoxicity against WT1-expressing leukemia cells in an HLA-DPB1*05:01-restricted manner." (PMID 36939853, 2023). "In another study, a gene that is often improperly over-expressed in leukemia and solid tumors, the Wilms tumor 1 (WT1) gene, was considered for the ES approach." (PMID 37834310, 2023). "In fact, both TCR-transduced CD4+ T cells effectively lysed WT1332 peptide-pulsed B-LCL and WT1-expressing HLA-DPB1*05:01-positive leukemia cell line, C2F8-CIITA." (PMID 36939853, 2023). "Conversely, in the ongoing WT1 peptide-based immunotherapy phase I/II trials, frequent clinical responses and even drastic tumor regression have been reported for leukemia, myelodysplastic syndrome and solid tumors, such as lung and breast cancers." (PMID 35453662, 2022). "HL-60 cells naturally express high levels of WT1 and are a preferential model for studying leukemia differentiation." (PMID 36500358, 2022). "WT1 is an intracellular antigen highly expressed in the bone marrow of patients with leukemia, particularly those with AML, myelodysplasia (MDS), and CLL." (PMID 35356211, 2022). "Several studies have confirmed that WT1 expression before and/or after allogeneic transplantation predicts leukemia relapse." (PMID 36119469, 2022). "In a phase 1/2 trial, 4 out of 4 leukemia patients who received WT1-specific CTL generated in the presence of IL-21 demonstrated both relapse-free survival without GvHD and did not need further anti-leukemic treatment." (PMID 35432319, 2022). "Exposure of WT1 antigen-specific donor-derived CD8+ T cells to IL-21 resulted in prolonged remission of patients with leukemia." (PMID 35356211, 2022). "Multiple human cancer cell culture experiments, derived from both leukemias and solid neoplasms, have shown that neutralization of WT1 via targeted antisense oligomers and small interfering (si)RNA abolished further tumor cell division." (PMID 35453662, 2022). "WT1 vaccines against breast cancer and other types of cancer such as lung, leukemia and pancreatic cancer are currently under phase I or phase II clinical trials highlighting its value in precision medicine." (PMID 36699376, 2022). "In vitro studies and WT1 peptide vaccine trials of patients with leukemias and various types of solid tumors have demonstrated that cytotoxic activity of WT1-specific CD8+ T cells can be induced by these stimuli." (PMID 36824620, 2022). "Several therapeutic approaches describe WT1-based vaccination as a potential strategy to boost anti-cancer immunity by induction of leukemia-specific immune response." (PMID 35476127, 2022). "WT1-specific CTLs showed specific cytotoxicity against leukemia cells and achieved sustained remission in patients with refractory AML." (PMID 35356211, 2022).
leukemia (continued). "Subsequent studies have shown that in addition to leukemia cells, WT1 is overexpressed in a number of solid tumors, including tumors of the lung, breast, and colon, and can be used as a malignant tumor antigen for these tumors." (PMID 35915803, 2022). "Despite mounting evidence demonstrating high levels of WT1 expression in leukemia and solid tumors the exact functional implications of increased WT1 expression in tumorigenesis are not fully understood." (PMID 35465313, 2022). "This study aims to observe the differentiating effect of shikonin on Wilms’ tumor 1 (WT1)-positive HL-60 cells and investigate the fate of the differentiated leukemia cells." (PMID 36500358, 2022). "The success of WT1-specific CTLs and WT1-specific TCR-T cells for eliminating leukemia cells was demonstrated in vitro and in xenograft models several years ago." (PMID 35356211, 2022). "Overexpression of leukemia-associated antigens such as proteinase-1 (PR1) and Wilm’s tumor-1 (WT1) have also been reported." (PMID 34804065, 2021). "CML cells express both leukemia-specific antigen derived from the BCR-ABL fusion protein and leukemia-associated antigens, including Wilms tumor 1(WT1), proteinase 3 (PR1), and preferentially expressed antigen of melanoma (PRAME)." (PMID 34771599, 2021). "A clinical study on WT1-mutated AML refractory to induction chemotherapy suggested the use of vitamin C as adjunct therapy, based on the evidence that WT1 mutant leukemia cells show low 5hmC levels that in turn indicate reduced TET2 activity." (PMID 33804775, 2021). "The A1505T mutation in TET2 disrupts this interaction, consequently leading to an effect on WT1 target genes expression and increased leukemia cell proliferation." (PMID 33395407, 2021). "Given the epigenetic alterations catalogued in WT1 mutant, epigenetic-targeted therapy has been explored as a potential mechanism to deal with this subgroup of leukemia." (PMID 33968731, 2021). "At present, the WT1 gene is used as the basis for the initial diagnosis of leukemia, the judgment of prognosis, and the need for hematopoietic stem cell transplantation." (PMID 33659248, 2021). "WT1 mutations are frequently found in de novo AML, especially in younger patients and in FLT3-ITD or CEBPA mutated leukemias." (PMID 33917307, 2021). "Wilms’ tumor 1 (WT1) has been one of the most widely explored vaccine targets in AML, since it is a leukemia-associated protein overexpressed in leukemic cells with a pivotal role in blast proliferation and differentiation." (PMID 35083154, 2021). "The 62-64 kDa WT1 protein isoform is not essential for normal development and reproduction in mice, while the 36-38 kDa WT1 protein isoform has more oncogenic potential than the WT1 52-54 kDa protein isoform in leukemia cells." (PMID 34845427, 2021). "In particular, in two early studies a WT1 peptide vaccine was capable of inducing WT1-specific cytotoxic CD8+ T cells, which was associated with some clinical responses, including stabilization of leukemia and achievement of MRD negativity." (PMID 34041025, 2021). "In this study, we designed a new WT1-siRNA and delivered to the K562 leukemia cells by using the pPRIME-CMV-GFP-FFs lentiviral vector system." (PMID 33110919, 2020). "This work demonstrated the achievement of using a newly designed siRNA against WT1 gene to inhibit endogenous WT1 expression in K562 leukemia cells." (PMID 33110919, 2020). "We found that wt1 is highly expressed in LICs and LSCs and facilitates the maintenance of leukemia in a murine MLL-AF9-induced model of AML." (PMID 32580769, 2020). "It has been shown that WT1 is expressed in various kinds of human cancer including leukemia and myelodysplastic syndrome, brain tumors, neuroblastoma, lung cancer, breast cancer, soft tissue sarcoma as well as in gynecological tumors such as ovarian carcinoma." (PMID 32859123, 2020).